GREB1 (growth regulating estrogen receptor binding 1)
Description:
May play a role in estrogen-stimulated cell proliferation. Acts as a regulator of hormone-dependent cancer growth in breast and prostate cancers.
Synonyms: KIAA0575
Tractability: Antibody: UniProt predicts a signal peptide or a membrane-spanning region.
Gene: Protein-coding gene on chromosome 2 (11,482,341 to 11,642,789, forward strand). Ensembl gene ENSG00000196208.
Subcellular location: Membrane
Subcellular location (Human Protein Atlas): Cytosol; Mitochondria
Pathways (Reactome):
Signal Transduction: Estrogen-dependent gene expression
Gene Ontology:
Biological process: morphogenesis of an epithelium
Cellular component: extracellular exosome; nucleoplasm; membrane
Genetic constraint (gnomAD): Loss-of-function variants: 101 observed, 184.64 expected, observed/expected ratio (o/e) 0.55, 90% interval 0.47 to 0.64. The upper end of that interval is the gene's LOEUF score, 0.64, which puts it in group 2 of 6, group 1 being the genes least tolerant of losing a copy. Missense variants: 2,115 observed, 2,493.8 expected, observed/expected ratio (o/e) 0.85, 90% interval 0.82 to 0.88. Synonymous variants: 1,078 observed, 1,066.7 expected, observed/expected ratio (o/e) 1.01, 90% interval 0.96 to 1.06.
Homologues: Orthologues: chimpanzee GREB1 (99% identical), macaque GREB1 (98% identical), dog GREB1 (92% identical), pig GREB1 (91% identical), mouse Greb1 (89% identical), rat Greb1 (89% identical), guinea pig GREB1 (79% identical), tropical clawed frog greb1 (68% identical), zebrafish greb1 (58% identical). Paralogues in human: GREB1L (50% identical).
Diseases named in the same sentence as GREB1 in open-access papers:
GREB1 is named in the same sentence as 54 diseases in open-access papers, as found by Europe PMC text mining. Sharing a sentence is not in itself a finding about the gene and the disease. The quoted sentences say what the papers report.
breast carcinoma (98 papers, 2004 to 2026). "Among these genes, GREB1 (growth regulating estrogen receptor binding 1) encodes a transcription factor known to be a crucial estrogen receptor (ER) regulatory factor and oncoprotein in ER+ breast cancer." (PMID 37611092, 2023). "We selected basally regulated genes (CCND1, PDK4, GREB1) encoding critical regulators of breast cancer progression, and performed RT-qPCRs in unstimulated T47D cells." (PMID 36076907, 2022). "GREB1 encodes growth regulation by estrogen in breast cancer 1, a protein transcriptionally driven by estrogen-bound ER." (PMID 32921307, 2020). "We showed that a single CpG overlapping the transcription start region of the GREB1 gene is associated with heritable breast cancer risk." (PMID 29491469, 2018). "At cg18584561 (GREB1), which was trimodal, both the hypomethylated and hypermethylated peaks were associated with decreased breast cancer risk (OR = 0.60 (95% CI: 0.45–0.80), and OR = 0.56, (95% CI: 0.34–0.95), respectively)." (PMID 29491469, 2018). "One of the heritable methylation marks associated with breast cancer risk was located close to the 5′ end of the gene Growth Regulation by Estrogen Breast Cancer 1 (GREB1)." (PMID 29491469, 2018). "In breast carcinomas, expression of GREB1 and AREG was associated with serum estradiol in all cancers and in the subgroup of estrogen receptor positive cases." (PMID 21812955, 2011). "The reports found that the Greb1 (gene regulated by estrogen in breast cancer protein) and Esrrb (estrogen related receptor, beta) is closely relative to estrogen stimulation." (PMID 39210919, 2024). "Given that GREB1 acts as an estrogen receptor coactivator in breast cancer cells, we postulated that GREB1 functions as a PR cofactor in the endometrium." (PMID 38431630, 2024). "GREB1 expression is positively correlated with ERα status in breast cancer cell lines and primary breast tumors." (PMID 39570927, 2024). "GREB1 was originally identified as an early prototypical estrogen-responsive gene that promotes estrogen-dependent proliferation of breast cancer cells and acts as a chromatin-bound estrogen receptor cofactor in these cells." (PMID 38431630, 2024). "Accordingly, GREB1 plays a pivotal role in those hormone-stimulated cell growth and transformation, including ER+ breast cancer, ovarian cancer, and prostate cancer, as well as endometrial stromal decidualization." (PMID 37611092, 2023). "GREB1 significantly affects the proliferation of estrogen receptor-α, which is a driving transcription factor in breast cancers and influences drug response." (PMID 37426199, 2023). "Growth regulation by estrogen in breast cancer 1 (GREB1) is a gene induced by estrogen in MCF7 breast cancer cells." (PMID 37658191, 2023). "We have previously demonstrated that Greb1 is upregulated by both ERα and ERβ (exogenous) in breast cancer MCF-7 cells." (PMID 38031019, 2023). "We then analysed the mRNA expression levels of 18 immuno-response genes alongside growth regulation by oestrogen in breast cancer 1 (GREB1), which has been reported to be an oestrogen receptor-regulated gene." (PMID 36016428, 2022). "GREB1 can limit the growth of hormone-sensitive breast cancer cells by modulating the PI3K/Akt signaling pathway." (PMID 36262352, 2022). "A more recent study showed that when knocking down GREB1, the proliferation of estrogen-dependent breast cancer cells is rescued by the expression of Akt constitutively across the direct link between estrogen signaling and the PI3K pathway." (PMID 36555156, 2022). "GREB1 is a target gene for ER regulation, and it relates to estrogen level in patients with breast cancer." (PMID 36262352, 2022). "An optimal level of GREB1 expression is necessary for the proliferation of breast cancer cells through PI3K/Akt/mTOR pathway signaling." (PMID 36555156, 2022).
breast carcinoma (continued). "Among the top hits, the PGR (progesterone receptor), GREB1 (growth regulation by estrogen in breast cancer 1), and BECN1 mRNAs were validated." (PMID 33542201, 2021). "In young women with breast cancer, GREB1 expression was significantly higher than that observed in a cohort of older patients." (PMID 32549322, 2020). "RSPO1 upregulates the expression of Esr1 and ERα signaling targets Pgr and Greb1 (growth regulation by estrogen in breast cancer 1) in a dose-depending manner." (PMID 32749219, 2020). "The proto-oncogene products, c-myc, GREB1, and TFF1 have been implicated in the cellular proliferation, metastasis, and migration of breast cancer cells." (PMID 33177647, 2020). "GREB1 was first reported as an estrogen-regulated gene in breast cancer then shown to bind directly to ER, presumably through its LxxLL motif, and function as an ER coactivator by promoting interaction with cofactors." (PMID 30644358, 2019). "An example of such a marker is the GREB1 gene in estrogen receptor (ER)-positive breast cancers, which is coregulated by ER and CDK8/19 in this tumor type." (PMID 31717492, 2019). "GREB1 (growth regulating estrogen receptor binding 1) is an early estrogen-responsive gene, and its expression correlates with estrogen levels in breast cancer patients." (PMID 31614463, 2019). "In breast cancer, GREB1 functions as a coactivator through binding to ER and recruitment of the EP300/CBP complex to ER target genes." (PMID 30644358, 2019). "We next examined the expression of three estrogen-responsive genes in these two cell lines; namely Growth Regulation By Estrogen In Breast Cancer 1 (GREB1), Cyclin D1 (CCND1) and Trefoil Factor 1 (TTF1)." (PMID 30370249, 2018). "Growth regulation by estrogen in breast cancer 1 (GREB1) promotes growth by estrogen-dependent proliferation of (breast cancer) cells." (PMID 30692930, 2018). "The younger (age ≤ 45 years) group of breast cancer patients who had higher estrogen levels showed significantly higher GREB1 expression than the older (age ≥ 70 years) group." (PMID 30154312, 2018). "In Tamoxifen-resistant breast cancer tissues, the GREB1 promoter becomes more methylated via the action of the histone lysine N-methyltransferase EZH2, leading to the epigenetic downregulation of GREB1." (PMID 30154312, 2018). "GREB1 expression correlates with ESR1 positivity in breast cancer cell lines and primary breast tumours, and GREB1 is induced by ESR1 binding to estrogen response elements (EREs) upstream of the GREB1 promoter." (PMID 29973689, 2018). "Microarray analysis identified Greb1 (Growth regulation by estrogen in breast cancer 1) as a highly E2-upregulated gene in tumours from an E2-responsive mouse model of ovarian cancer." (PMID 29973689, 2018). "One of these E2-regulated genes, GREB1, is particularly promising based on its role in E2-stimulated breast cancer cell proliferation." (PMID 29973689, 2018). "Further evidence for the role of GREB1 in breast cancer comes from studies of the cells’ responses to Tamoxifen." (PMID 30154312, 2018). "GREB1 is an early estrogen-responsive gene, and its expression is correlated with estrogen levels in breast cancer patients." (PMID 30154312, 2018). "In this study, we quantified the dynamics of nascent transcription from an endogenous GREB1 locus in individual breast cancer cells and demonstrated that estrogen‐controlled transcription occurs in bursts." (PMID 29476006, 2018). "Several genes that correlate with ESR1 in breast cancer do not show a similar correlation in ovarian cancer, and in breast cancer, GREB1 and other E2-regulated genes correlated with serum E2 changes throughout the menstrual cycle." (PMID 29973689, 2018). "Breast cancer cells initially respond to Tamoxifen, which antagonizes the ER and leads to decreased GREB1 expression." (PMID 30154312, 2018). "Previous studies in endometriosis and breast cancer reported that GREB1 is mainly nuclear, which supports its role as an ESR1 cofactor." (PMID 29973689, 2018).
breast carcinoma (continued). "GREB1 was first discovered in brain tissue and later identified as an early estrogen-responsive gene in breast cancer." (PMID 30154312, 2018). "GREB1 is a central mediator of estrogen‐induced cell growth in vitro and is a marker of tumor growth in estrogen‐sensitive breast cancers." (PMID 29476006, 2018). "Estrogen is a key mediator in the development and progression of breast cancer, and several studies indicate that ER regulates GREB1 expression." (PMID 30154312, 2018). "GREB1 a protein which is originally upregulated in ER + breast cancers such as MCF-7 cells and results in upregulation of ER survival signaling through the growth factor ligand, resulting in increased growth and proliferation." (PMID 29085821, 2017). "Our results provide further support for association at the 2p25.1 locus, containing an oestrogen-regulated gene, GREB1, that was first identified in breast cancer cell lines and tumours." (PMID 28537267, 2017). "In the canonical model of the ERα signaling pathway, E2‐bound ERα forms a homodimer that binds DNA at estrogen‐response elements (EREs), recruits NCOA1/2/3, and activates the GREB1 gene, which is required for proliferation of ERα‐positive breast cancer cells." (PMID 27107013, 2016). "Completely blocking AF‐2 with an extended side chain or altering the shape of AF‐2 changes the preference away from NCOA1/2/3 for determining GREB1 levels and proliferation of breast cancer cells." (PMID 27107013, 2016). "We showed that alcohol further increased GREB1 expression after estrogen treatment, suggesting that alcohol promotes hyper-activation of estrogen signaling in breast cancer cells." (PMID 26661278, 2015). "Depletion of either CHD1, GREB1 or KPNA2 significantly abrogated the enhanced growth of ER+ breast cancer cells due to miR-26 depletion." (PMID 24735615, 2014). "The expression of CHD1, GREB1 or KPNA2 was required for estrogen-stimulated breast cancer cell growth." (PMID 24735615, 2014). "Growth regulation by estrogen in breast cancer 1 (GREB1) plays an important role in the regulation of proliferation of breast cancers." (PMID 24727858, 2014). "Another estrogen receptor target gene, GREB1 (growth regulation by estrogen in breast cancer 1), is involved in the estrogen induced proliferation of breast cancer cells and has the potential of being a clinical marker for response to endocrine therapy." (PMID 23305139, 2013). "Regulation of GREB1 expression, which plays a role in estrogen-induced proliferation of breast cancer cells, is mediated by binding of ERα to three consensus EREs spread over approximately 20 kb of upstream flanking sequences of GREB1." (PMID 24349450, 2013). "Recently a monoclonal antibody for GREB1 was created, allowing the detection of a 216 kDa protein whose expression positively correlated to ERα expression in breast cancer cell lines and tumor samples, as well as to GREB1 mRNA transcript levels." (PMID 22359603, 2012). "In the ER-negative breast cancer cell line MDA-MB-231 cells, LRH-1 over-expression caused a significant, 26-fold increase in GREB-1 expression." (PMID 22359603, 2012). "GREB1 is previously found to be an important estrogen-induced stimulator of growth in ER+ breast cancer cell lines." (PMID 21812955, 2011). "In this study, we show that XAP2 is recruited to the promoter of ERα regulated genes like the breast cancer marker gene pS2 or GREB1 and negatively regulate the expression of these genes in MCF-7 cells." (PMID 21984905, 2011). "In MCF-7 cells, we observed a negative regulatory effect of XAP2 on the breast cancer marker gene pS2 as well as GREB1, another ER target gene." (PMID 21984905, 2011). "GREB1 expression is regulated by ERα in breast cancer and by TCF4 in hepatoblastoma." (PMID 37658191, 2023). "Interestingly, Greb1, which is upregulated both by ERα and ERβ (engineered expression,) in human breast cancer cells, was found among these genes." (PMID 38031019, 2023).
breast carcinoma (continued). "We find that GREB1 is highly expressed in MNA+ NB at levels comparable to ER+ breast cancer." (PMID 37611092, 2023). "It has also been documented that CTSD and GREB1 were increased in breast cancer patients." (PMID 33861751, 2021). "Initially named as KAA0575 and further renamed as Growth Regulation by Estrogen in Breast Cancer 1 (GREB1), the GREB1 gene is a key intermediary for the estrogen-stimulated proliferation of breast cancer cells and the androgen-stimulated proliferation of prostate cancer cells." (PMID 32549322, 2020). "ERα directly controls GREB1 expression, and GREB1 is required for breast cancer cell growth." (PMID 31408468, 2019). "Those include SNPs associated with endometriosis identified regions near the gene for ERα, regions upstream of the beta subunit of follicle-stimulating hormone (FSH), and the Growth Regulating Estrogen Receptor Binding 1 (GREB1), previously associated with breast cancer." (PMID 31717614, 2019). "As zearalenone and apigenin activated ERs, we tested the potential effect of these molecules on the expression of endogenous E2-dependent genes, such as the chemokine CXCL12, the progesterone receptor (PgR), amphiregulin (AREG) and growth regulation in breast cancer 1 (GREB1)." (PMID 30678243, 2019). "Second, in breast cancer patients, GREB1 expression correlated with estrogen levels." (PMID 30154312, 2018). "Interestingly, SRC-3 is reported to interact with growth regulation by estrogen in breast cancer 1 (GREB1) and increase estrogen-induced transcription in breast cancer cell line MCF-7 cells." (PMID 30154312, 2018). "This difference from breast cancer may reflect tissue-specific regulation of GREB1 and/or the postmenopausal status of most ovarian cancer patients." (PMID 29973689, 2018). "GREB1 loss has been linked to tamoxifen resistance in ESR1+ breast cancer and cell lines; however, the effects of GREB1 expression in ESR1− cell lines have not been examined." (PMID 29973689, 2018). "Growth regulation by estrogen in Breast Cancer 1 (GREB1) (fold change=-2.81 in our data) interacts with estrogen receptor (ER) in half of ER positive primary breast cancers; however, how could it interact with ESR1 in TNBC remains unknown." (PMID 30175120, 2018). "However, in Tamoxifen-resistant breast cancer tissues, the GREB1 promoter becomes more methylated via the action of the histone lysine N-methyltransferase EZH2, leading to the epigenetic downregulation of GREB1." (PMID 30154312, 2018). "GREB1 (Growth regulation by estrogen in breast cancer 1) is an ESR1 (estrogen receptor 1)-upregulated protein which may mediate estrogen action." (PMID 29973689, 2018). "Potential oncogenes amplified in the breast cancer include GREB1, NRXN1, MGAT5, PKP4, DAPL1, ITGB6, and RBMS1, which may be implicated in carcinogenesis, proliferation, and invasion." (PMID 26432421, 2015). "Moreover, we analyzed the expression of the ER target genes progesterone receptor (PR) and GREB1 (growth regulation by estrogen in breast cancer 1) and asked if downregulation of ER protein following BCL9-2 knockdown also affects ER target gene expression." (PMID 25149534, 2014). "Interestingly, both AREG and GREB1 were up-regulated in ER+ breast carcinomas of younger (< 45 years) compared with older (> 70 years) women in a previous publication." (PMID 21812955, 2011). "GREB1, in combination with other genes, also predicted recurrence of tamoxifen-treated breast cancer, as results confirmed in vitro as tamoxifen-resistant breast cancer cells showed a decrease in GREB1 expression while reestablishing GREB1 expression recovered sensitivity to tamoxifen." (PMID 32549322, 2020). "In addition, the expression of another ERα-regulate gene GREB1 (growth regulation by estrogen in breast cancer 1) is also increased upon XAP2 depletion in MCF-7 cells (compare Scr E2 and hsiXAP2 E2), suggesting a suppressive effect of XAP2 on the expression of ERα target genes." (PMID 21984905, 2011).